IRF9 (interferon regulatory factor 9)
Diseases named in the same sentence as IRF9 in open-access papers (continued):
Sharing a sentence is not in itself a finding about the gene and the disease.
glioblastoma (3 papers, 2018 to 2022). The most malignant astrocytic tumor (WHO grade IV). "In glioblastoma-derived T98G cells, IRF9 overexpression enhanced the antiproliferative activity of IFN-α2c in resistant cells and induced apoptosis." (PMID 36552831, 2022). "Moreover, studies by Lee, Ramaswamy, and Bredel all found that IRF8 and IRF9 levels were significantly increased in glioblastoma or anaplastic oligoastrocytoma." (PMID 33902005, 2021). "In addition, general screening of candidate genes revealed that increased expression of IRF9 and XRCC1 as genetic biomarkers are predicative of glioblastoma multiform progression." (PMID 30147694, 2018).
glioma (3 papers, 2020 to 2022). A benign or malignant brain and spinal cord tumor that arises from glial cells (astrocytes, oligodendrocytes, ependymal cells). "We found that IRF1, IRF2, IRF5, IRF7, IRF8, and IRF9 were upregulated in glioma compared with normal tissue." (PMID 33902005, 2021). "We found that IRF1, IRF2, IRF5, IRF8 and IRF9 were significantly upregulated in glioma compared to normal brain tissue." (PMID 33902005, 2021). "In summary, this study showed that IRF1, IRF2, IRF5, IRF8, and IRF9 mRNA levels were increased in glioma compared to normal tissue." (PMID 33902005, 2021). "Collectively, these results indicate that IRF family members, including IRF1, IRF2, IRF5, IRF8 and IRF9, may serve as prognostic biomarkers and indicators of immune status in glioma patients." (PMID 33902005, 2021). "Overall survival curves indicated that glioma patients with lower IRF1 (p = 4.42E-33), IRF2 (p = 2.22E-16), IRF3 (p = 1.43E-15), IRF4 (p = 0.004), IRF5 p = 5.84E-12), IRF7 (p = 6.85E-28), IRF8 (p = 0.001), and IRF9 (p = 0.000) transcript levels had significantly longer overall survival times." (PMID 33902005, 2021). "Among the 260 grade II, 267 grade III, and 173 grade IV glioma patients, significant correlations were observed between IRF1 (p = 8.00E-61), IRF2 (p = 6.80E-18), IRF3 (p = 1.70E-23), IRF5 (p = 2.30E-08), IRF7 (p = 1.90E-29), IRF8 (p = 0.029), IRF9 (p = 4.80E-05) expression and pathological grade." (PMID 33902005, 2021).
Hepatic steatosis (3 papers, 2014 to 2025). Steatosis is a term used to denote lipid accumulation within hepatocytes. "In contrast, a similar study using IRF9-deficient mice demonstrated that IRF9 promotes insulin sensitivity and attenuates inflammation and hepatic steatosis." (PMID 32660130, 2020). "For instance, IRF9 has been reported to promote the transcription of Pparα, improving hepatic steatosis or inhibiting SIRT1 activity, thus mitigating liver ischemic injury." (PMID 40083324, 2025). "In hepatocytes, the decrease in IRF9 upon overnutrition aggravates hepatic steatosis and insulin resistance." (PMID 25319116, 2014).
hepatitis C (3 papers, 2010 to 2024). "IRF9 and LINC01089 in pulmonary arterial hypertension are related to the regulation of signaling pathways like MAPK, NOTCH, human papillomavirus, and hepatitis c infection." (PMID 39791702, 2024).
herpes simplex infection (3 papers, 2021 to 2022). "After treatment of a metastatic BC patient with herpes simplex infection pathway (associated KGs: OAS1, OAS3, ATF6B, IRF9), there has created a case of Sweet Syndrome." (PMID 35617355, 2022).
leukemia (3 papers, 2021 to 2022). A malignant (clonal) hematologic disorder, involving hematopoietic stem cells and characterized by the presence of primitive or atypical myeloid or lymphoid cells in the bone marrow and the blood. "The induction of IRF9 expression in NB4 cells can promote cell differentiation as well as reduce the colony forming ability of leukemia cells, implying an anti-leukemia effect for IRF9, which lays a biological foundation for IRF9 as a potential target for the treatment of APL." (PMID 35680593, 2022). "Some studies reported the tumor suppressive properties of IRF9, such as the facilitation of the antiproliferative effects of IFN in prostate cancer cells, reduced tumor growth in renal clear cell carcinoma, and effects in leukemia." (PMID 33430083, 2021).
lung adenocarcinoma (3 papers, 2020 to 2025). A carcinoma that arises from the lung and is characterized by the presence of malignant glandular epithelial cells. "We performed in vitro and in vivo experiments to reveal the oncogenic properties of IRF9, which was highly upregulated in lung adenocarcinoma." (PMID 33430083, 2021). "In lung adenocarcinoma (LUAD), IRF9 induced PD-L1 upregulation upon IFNβ stimulation, which indicates the presence of an immunosurveillance escape mechanism." (PMID 33430083, 2021).
prostate carcinoma (3 papers, 2013 to 2024). A carcinoma that arises from epithelial cells of the prostate gland. "In acute myeloid leukemia and prostate cancer, IRF9 acts as a tumor suppressor; in pancreatic diseases, it acts as an oncogene." (PMID 33430083, 2021). "Combining existing reports with the analysis presented in this study, it can be inferred that RORC, AR, LIN28B, IRF9, and IRF3 promoted prostate cancer lineage plasticity through the RTK/RAS pathway." (PMID 38778150, 2024). "RORC, AR, LIN28B, IRF9, and IRF3 exert promotive roles in prostate cancer." (PMID 38778150, 2024). "However, in prostate cancer, IL6 itself induced IRF9 expression and IRF9 mediated the antiproliferative effects of IFNα2." (PMID 33430083, 2021).
tuberculosis (3 papers, 2009 to 2024). A chronic, recurrent infection caused by the bacterium Mycobacterium tuberculosis. "In the current study, six genes (IFITM1, IRF9, MX1, OAS1, STAT1, and STAT2) of the “host response signature network” are significantly overlapping with the “human immune response to tuberculosis” pathway with p-value 1.57e-8." (PMID 33362771, 2020). "In order to investigate the mechanisms of these responses, we used nebulized rIFN-γ1b in eleven drug-sensitive tuberculosis patients, and found an increase in signaling molecules STAT-1, IRF-1 and IRF-9." (PMID 19753300, 2009).
acute myeloid leukemia (2 papers, 2019 to 2021). Acute myeloid leukemia (AML) is a group of neoplasms arising from precursor cells committed to the myeloid cell-line differentiation. "However, our findings are consistent with recent reports documenting the role of IRF9 in the negative regulation of the TRIF/NF-κB transcriptional response or the expression of SIRT1 in acute myeloid leukemia cells." (PMID 31426476, 2019).
bronchitis (2 papers, 2019 to 2024). An acute or chronic inflammatory process affecting the bronchi. "Whole exome sequencing of 20 children identified a variant in the gene encoding interferon regulatory factor 9 (IRF9) in a 2-year-old child who had previously suffered from bronchitis and biliary perforation." (PMID 31488196, 2019).
diffuse large B-cell lymphoma (2 papers, 2018 to 2019). "Notably, a recent publication including ChIP-seq data from two diffuse large B-cell lymphoma cell lines shows STAT3 enrichment at this location in the IRF9 promoter, although, in this case STAT3 appeared to negatively regulate IRF9 transcription." (PMID 30679726, 2019).
hepatoma (2 papers, 2020 to 2021). "We establish, based on quantitative measurements obtained for the hepatoma cell line Huh7.5, an ordinary differential equation model for IFNα signal transduction that comprises the feedback regulators STAT1, STAT2, IRF9, USP18, SOCS1, SOCS3, and IRF2." (PMID 32696599, 2020).
Insulin resistance (2 papers, 2021 to 2024). Increased resistance towards insulin, that is, diminished effectiveness of insulin in reducing blood glucose levels. "IRF9 regulates interferon-driven gene expression, and alleviates hepatic insulin resistance, steatosis and inflammation through interaction with PPARα." (PMID 39350187, 2024). "In high-fat-diet models IRF9 was shown to regulate expression of fatty acid (FA) metabolism genes and in this way protect from hepatic steatosis and insulin resistance." (PMID 34237114, 2021).
Listeria monocytogenes infection (2 papers, 2019 to 2021). "Understanding the metabolic pathways controlled by IRF9 and IFN-I during L. monocytogenes infection might lead the way to a better understanding of listeriosis." (PMID 34237114, 2021). "Interestingly, the IRF9, STAT1, STA3, and NF-κB can bind to promoter region of Nos2 gene and induce its transcription during Listeria monocytogenes infection, suggesting both direct and indirect routes for miR-302d regulation of Nos2 expression." (PMID 30949455, 2019).
ovarian carcinoma (2 papers, 2022 to 2023). A malignant neoplasm originating from the surface ovarian epithelium. "Regarding IRF9 action in ovarian cancer cells, this protein was also reported to be the key upstream regulator mediating growth-inhibitory effects of IFNα on OVCAR-3 cells, which supports our data suggesting a direct link between IRF9 induction and OVCAR-3 growth inhibition." (PMID 36077645, 2022). "A tumor-suppressive effect of chemerin was also reported by a recent in vitro study demonstrating chemerin to reduce the growth of ovarian cancer cell spheroids via activating the release of interferon (IFN)α, leading to induction of a broad, IRF9/ISGF3-mediated anti-tumoral transcriptome response." (PMID 36900088, 2023).
Primary Sjogren Syndrome (2 papers, 2022). "Additionally, genes related to type I-IFN activity including, ICSBP1, MX1, IFITM1, IFITM2, IRF9, were found to be overexpressed in patients with Sjogren’s syndrome." (PMID 36059459, 2022).
promyelocytic leukaemia (2 papers, 2016 to 2022). "We then induced the expression of IRF9 in NB4, a promyelocytic leukemia cell line." (PMID 35680593, 2022).
small cell lung carcinoma (2 papers, 2022 to 2024). Small cell lung cancer (SCLC) is a highly aggressive malignant neoplasm, accounting for 10-15% of lung cancer cases, characterized byrapid growth, and early metastasis. "Additionally, the expression levels of U-STAT1, U-STAT2, and IRF9 in small cell lung carcinoma (SCLC) cell lines correlate with survival after DNA-damaging chemotherapy." (PMID 39062738, 2024). "Additionally, we observed an increase in the expression of IRF9 and STAT2 of the IFN signalling pathway within the paediatric diffuse glioma cell lines, suggesting activation of an inflammatory stress response shown to decrease chemosensitivity in small cell lung cancer cells." (PMID 36010867, 2022).
uterine tumour (2 papers, 2014). "The overexpression of IRF9 has been observed in almost half of breast and uterine tumours." (PMID 24270600, 2014).
B cell lymphoma (1 paper, 2025). "STAT3 inhibition also synergized with inducers of type I IFN, a downstream effector of the cGAS-STING pathway, to effectively inhibit B cell lymphoma growth, possibly by alleviating the suppressive effects of STAT3 on IRF7, IRF9, STAT1, and STAT2 expression." (PMID 40743845, 2025).
chordoma (1 paper, 2025). Chordomas are rare malignant tumors arising from embryonic remnants of the notochord in axial skeleton. "In addition, all chordoma cell lines expressed IRF9, which forms a complex with activated STAT1 and STAT2 that stimulates the transcription of ISGs." (PMID 40901948, 2025).
co-infection (1 paper, 2014). "Importantly, co-infection with AdSIRT1 largely abolished the promoting effects of IRF9 on Cyclin D1 and MMP9 promoter activities." (PMID 25319116, 2014). "Co-infection with AdshSIRT1 largely abolished the protective effect of IRF9 inhibition." (PMID 25319116, 2014).
colorectal tumour (1 paper, 2019). "We also report a positive correlation between STAT3 and IRF9 protein abundance in primary colorectal tumour samples and cell lines." (PMID 30679726, 2019).
demyelination diseases (1 paper, 2017). "Indeed, IRF7 is a significant regulatory factor in the development of demyelination diseases in the CNS, such as MS and EAE33, whereas IRF9 is important in injury-induced type 1 IRF signaling, which regulates inflammatory responses in the CNS50." (PMID 28747667, 2017).
fibrosarcoma (1 paper, 2019). A malignant mesenchymal fibroblastic neoplasm affecting the soft tissue and bone. "Using RNAi to knockdown STAT1 in HCT116 cells and U3A, a STAT1-null sub-line of fibrosarcoma cell line 2fTGH, we previously showed that STAT1 was not required for, but augmented, the expression of IRF9 and IRDS genes induced by high cellular density." (PMID 30679726, 2019).
H1N1 virus infections (1 paper, 2017). "The H7N9, H7N7 and H5N1 infected mouse lung transcriptome also showed higher levels of CXCL13, IL-6, IFNG, IFNB1, IRF9, IRF1, and TNF compared with 2009 pandemic H1N1 virus infections." (PMID 28558796, 2017).
head and neck cancer (1 paper, 2024). A primary or metastatic malignant neoplasm affecting the head and neck. "In head and neck cancer, both IRF7 and IRF9 have been reported to be overexpressed." (PMID 39329063, 2024).
Hepatic fibrosis (1 paper, 2023). The presence of excessive fibrous connective tissue in the liver. "In another study characterizing molecular changes associated with early hepatic fibrosis, STAT2/IRF9 expression was found to be increased in diseased livers of patients with hepatic fibrosis, compared with healthy control livers." (PMID 36671504, 2023).
HIV-1 infection (1 paper, 2020). The type species of lentivirus and the etiologic agent of acquired immunodeficiency syndrome (AIDS). "Investigations on the phosphorylation status of STAT1, STAT2 and IRF9 in chronic HIV-1 infection are underway." (PMID 33064743, 2020).
insomnia (1 paper, 2025). A sleep disorder characterized by difficulty in falling asleep and/or remaining asleep. "Among these, IFI44, IFI44L, and IRF9, were identified as having a significant effect on diagnosing insomnia-associated uveitis." (PMID 39958336, 2025). "Our study identified the diagnostic significance of IFI44 and IRF9 in insomnia-associated AU; however, this study has some limitations." (PMID 39958336, 2025). "According to ROC curve analysis, the area under the curve of IFI44 and IRF9 was greater than 0.7 in both insomnia and uveitis." (PMID 39958336, 2025). "Our study demonstrated involvement of the viral response in both insomnia and AU and identified the diagnostic significance of IFI44 and IRF9 in these conditions." (PMID 39958336, 2025). "We speculate that elevated IRF9 in insomnia patients may promote the progression of uveitis by enhancing immune responses and the secretion of inflammatory cytokines." (PMID 39958336, 2025). "Additionally, further in-depth investigation of IFI44 and IRF9 involvement in insomnia and uveitis is warranted and IFI44 and IRF9 should be assessed as therapeutic targets." (PMID 39958336, 2025). "Finally, IFI44 and IRF9 expressions in PBMCs from subjects with insomnia with or without uveitis were confirmed by qPCR." (PMID 39958336, 2025).
ischemic stroke (1 paper, 2025). A stroke disorder caused by obstruction of blood flow to the brain, due to thrombotic (local blood clot formation) or embolic (due to a blood clot or other material traveling from another site) event. "In addition, other paralogs of IRF6, such as IRF4, IRF5, IRF8, and IRF9, have been linked to neuronal survival following ischemic stroke." (PMID 40149423, 2025).
liver cancer (1 paper, 2015). An epithelial or non-epithelial malignant neoplasm that arises from the liver. "While interferon stimulating gene IRF9 is a key factor forcing the anti-proliferative effect of IFN-α, ISG15 is involved in a Wnt/beta-catenin suppressing pathway and may inhibit liver cancer cell growth." (PMID 25504438, 2015).
liver diseases (1 paper, 2020). "Other studies regarding upstream regulators of SIRT1, such as IRF9/PPAR-α, NAMPT/NMNAT, HuR, AMPK, PARP1, CK2 and cathepsins have pointed to these proteins as possible therapeutic targets for the treatment of various inflammatory pathologies, including liver diseases." (PMID 32485811, 2020).
lymphoma (1 paper, 2025). A malignant (clonal) proliferation of B- lymphocytes or T- lymphocytes which involves the lymph nodes, bone marrow and/or extranodal sites. "Among them, the transcription factor IRF9 gets the highest enrichment in GM12878, and the IRF family TFs were reported to be crucial for the pathogenesis of lymphoma." (PMID 41021262, 2025).
meningoencephalitis (1 paper, 2024). Inflammation of the meninges and brain, generally secondary to an infectious cause. "Furthermore, interferon regulatory factor 9 (IRF9) deficiency was identified in a family suffering from multiple infections, with one miscarriage associated with DENV and ZIKV coinfection and one child presenting with HSV-1 meningoencephalitis." (PMID 38997413, 2024).
Myocardial fibrosis (1 paper, 2021). "In contrast to wildtype IRF9+/+mice, the IRF9−/−mice show worst cardiac hypertrophic and profibrogenic responses as evidenced by significantly elevated levels of ANP and β-MHC, and myocardial fibrosis." (PMID 34831061, 2021).
myocardial ischemia (1 paper, 2024). A disorder of cardiac function caused by insufficient blood flow to the muscle tissue of the heart. "IRF9 was upregulated in the heart tissue and modulated the cardiomyocyte death and inflammation development after myocardial ischemia reperfusion." (PMID 38894720, 2024).
myocarditis (1 paper, 2023). Myocarditis is a condition that is characterized by inflammation of the heart muscle (myocardium). "Consistent with the downregulation of motif activities of IRF3 and IRF7, peripheral immune cells showed a reduced motif activity level of STAT1::STAT2 and IRF9 at the time of myocarditis." (PMID 37264110, 2023).
osteoporosis (1 paper, 2025). A condition of reduced bone mass, with decreased cortical thickness and a decrease in the number and size of the trabeculae of cancellous bone (but normal chemical composition), resulting in increased fracture incidence. "The suppression of interferon regulatory factor 9 (IRF9) enhances the differentiation of osteoclasts, consequently hindering ferroptosis and potentially offering a new avenue for the treatment of osteoporosis." (PMID 41551515, 2025).
pancreatic adenocarcinoma (1 paper, 2024). "Pancreatic adenocarcinoma tumors exhibit increased levels of mRNA expression for components of the Transforming growth factor-β pathway (TGFB1/2/3, TGFBR1/2/3) and Interferon Type I pathways (IFNAR1, STAT1, IRF9 and IFI27)." (PMID 39457004, 2024).
plasmacytoma (1 paper, 2009). Plasmacytoma is a localized mass of neoplastic monoclonal plasma cells that represents approximately 5% of all plasma cell neoplasms. "Third, IRF9-/- mice treated with pristane developed fatal plasmacytomas as early as 6 months following pristane injection, whereas no IFNAR2-/- mice developed this phenotype." (PMID 19624844, 2009).
renal carcinoma (1 paper, 2025). A carcinoma arising from the epithelium of the renal parenchyma or the renal pelvis. "In functional assays, IRF9 knockdown impaired ccRCC proliferation and migration, whereas IRF9 overexpression enhanced these malignant traits, supporting its oncogenic role in renal cancer." (PMID 41403935, 2025).
renal cell adenocarcinoma (1 paper, 2021). A carcinoma arising from the renal parenchyma. "In a renal cell adenocarcinoma study, IRF9 knockdown was shown to increase tumor formation in a xenograft model, whereas the overexpression of both IRF9 and STAT2 reduced tumor growth." (PMID 33430083, 2021).
renal fibrosis (1 paper, 2023). A final common manifestation of a wide variety of chronic kidney diseases characterized by glomerulosclerosis and tubulointerstitial fibrosis. "Using a novel transgenic mouse strain in which MRTF-A was deleted from myofibroblasts, these investigators found that MRTF-A might rely on a transcriptional cascade consisting of ZEB1 and IRF9 to drive renal fibrosis." (PMID 37121967, 2023).